CBX3 (chromobox 3)
Diseases named in the same sentence as CBX3 in open-access papers (continued):
Sharing a sentence is not in itself a finding about the gene and the disease.
pancreatic cancer (continued). "Bioinformatic analyses through the GEPIA web tool revealed that CBX3, CBX1, and CBX5 were significantly overexpressed in the pancreatic cancer tissues than those in non-malignant pancreatic tissues (P < 0.01)." (PMID 35637952, 2022). "MTS and colony formation assays demonstrated that SMURF2 knockdown enhanced proliferation of pancreatic cancer cells; however, co-knockdown of SMURF2 and CBX3 could not reverse this process." (PMID 35637952, 2022).
osteosarcoma (18 papers, 2012 to 2023). A usually aggressive malignant bone-forming mesenchymal neoplasm, predominantly affecting adolescents and young adults. "In patients with osteosarcoma, CBX3 is overexpressed which is associated with larger tumor sizes, higher metastasis rates, and poor prognosis." (PMID 35210369, 2022). "CBX3 was associated with the poor prognosis and promoted tumorigenesis of osteosarcoma." (PMID 37436074, 2023). "CBX3 is significantly upregulated in osteosarcoma tumor stem cells and facilitates their self-renewal." (PMID 36361869, 2022). "further confirmed the function and role of HP1-γ (CBX3) in osteosarcoma, by showing that the expression of HP1-γ (CBX3) was associated with a poorer DFS and OS, as well as a larger tumor size, a higher distant metastasis rate, and a higher clinical stage." (PMID 34046352, 2021). "CBX3 has been previously identified as a potential biomarker for tumor stem cells in osteosarcoma, while CBX4 has been reported to induce hypoxia-mediated activation of VEGFA (vascular endothelial growth factor A) and angiogenesis in hepatocellular carcinomas." (PMID 28851357, 2017). "Consistently higher CBX3 protein expression in spheres as compared with monolayers was observed, indicating CBX3 as a marker for TSC-enrichment in osteosarcoma." (PMID 22870217, 2012). "CBX3 expression was significantly higher in both osteosarcoma and osteosarcoma metastasized to lung as compared with primary osteoblasts." (PMID 22870217, 2012). "In addition, other studies have shown that the overexpression of CBX3 in osteosarcoma, tongue squamous carcinoma and breast cancer can adversely affect the prognosis by promoting the occurrence as well as the development of tumors." (PMID 35573019, 2022). "In osteosarcoma, the CBX3 overexpression could regulate cell proliferation by stimulating the transformation of the G1/S cell cycle." (PMID 35573019, 2022). "In addition, elevated levels of CBX3 expression in tumor stem cell (TSC)-enriched osteosarcoma cultures was detected." (PMID 23874428, 2013). "In addition, consistently higher CBX3 expression in TSC-enriched osteosarcoma cultures was identified." (PMID 22870217, 2012). "Identification of ABCA5 and CBX3 in TSC-enriched spheres fulfilled our goal of finding osteosarcoma biomarker candidates that could be used in combination with already known markers, such as ABCG2 and ALDH." (PMID 22870217, 2012). "Possibly due to their mesenchymal origin, osteosarcoma CSCs are proved to preferentially express MSC markers, such as CD133, CD117/Stro-1, CBX3/ABCA5." (PMID 24893164, 2014). "Since stem-like cells in bone sarcoma were firstly detected by Gibbs, multiple markers have been employed to identify CSCs of osteosarcoma, such as CD133, CD117/Stro-1, CBX3/ABCA5." (PMID 24893164, 2014). "For both CBX3 and ABCA5, comparable expression was observed between osteosarcoma and osteosarcoma metastasized to lung." (PMID 22870217, 2012). "Through the study and the literature review, we found that a high expression of CBX3 might be a biomarker for poor prognosis in HCC, CRC, prostate cancer and osteosarcoma patients." (PMID 36140750, 2022). "In addition, proteomic and transcriptome analyses revealed high expression of chromobox protein homolog 3 (CBX3) and ABCA5, respectively, which was significantly higher in osteosarcoma than in primary osteoblast." (PMID 28115942, 2016). "In addition, high expression of CBX3 might be a biomarker for poor prognosis in HCC, CRC, prostate cancer and osteosarcoma patients." (PMID 36140750, 2022).
breast carcinoma (16 papers, 2014 to 2025). "The result indicated that the deletion in CBX3 was associated with breast cancer." (PMID 33431054, 2021). "We found that high CBX1 and CBX3 were associated with poor survival of breast cancer patients." (PMID 33082469, 2020). "The ERK signaling pathway, which includes proteins such as mitogen-activated protein kinase (MEK) and ERK and is directly influenced by CBX3, highlighting the importance of CBX3 in breast cancer progression." (PMID 40175347, 2025). "The mRNA expression of CBX3 has been found to affect the outcome of breast cancer in different subtypes." (PMID 33431054, 2021). "The result indicated that the DSVs in SNTG2, PCMT1, DACT2, CBX3, ATP11A, and SHC2 were associated with breast cancer." (PMID 33431054, 2021). "Human HP1 proteins, HP1α/CBX5, HP1β/CBX1, and HPγ/CBX3, correlated with proliferation, invasion, and metastasis by regulating gene expression in human breast cancer cells." (PMID 33082469, 2020). "CBX3 has recently been proposed to have a close relationship with the tumor, such as non-small cell lung cancer, prostate cancer and breast cancer among others." (PMID 28193906, 2017). "Moreover, in patients with HCC and breast cancers, CBX3 overexpression promotes the proliferation of tumor cells and is associated with poor prognosis." (PMID 35464847, 2022). "In breast cancer and liver cancer, CBX3 was identified to be highly expressed, and its overexpression could enhance tumor cell proliferation and predict a poor prognosis." (PMID 35210369, 2022). "CBX3 mRNA high expression was correlated to worsening RFS for all breast cancer patients." (PMID 33431054, 2021). "CBX3 was 2.498-fold elevated in breast cancer samples as compared with normal tissues (p=8.88E-9)." (PMID 29190923, 2017). "In addition, CBX3 was found overexpressed in breast cancer and non-small cell lung cancer tissues, and its expression may predict the poor prognosis of patients with these cancers." (PMID 29903985, 2018). "In addition, both CBX3 and C15orf57 were recurrently partnered with others in breast cancer." (PMID 25499959, 2014). "The results of the CPTAC dataset showed compared with the normal tissues, the primary tumors of breast cancer, colon cancer, ovarian cancer, clear cell RCC, LUAD, and UCEC had higher expression of CBX3 total protein (P < 0.001)." (PMID 35172803, 2022). "Also, other CBX family members like CBX3, CBX4, CBX5, CBX6, CBX7 and CBX8 express different patterns in breast cancer compared with other cancer types cells." (PMID 29190923, 2017).
hepatocellular carcinoma (15 papers, 2017 to 2024). A malignant tumor that arises from hepatocytes. "Results indicated that high expression of CBX2 and CBX3 proteins was significantly associated with poor prognosis for hepatocellular carcinoma patients." (PMID 35677563, 2022). "Univariate and multivariate analysis of the association of CBX3/HP1γ with survival and recurrence in patients with hepatocellular carcinoma." (PMID 31375643, 2019). "Furthermore, a previous study established an association between tumor stemness and CBX3 levels, and its overexpression was associated with higher mutational loads in pancreatic adenocarcinoma, lung adenocarcinoma, hepatocellular carcinoma, and endometrial cancer." (PMID 37674204, 2023). "High expression levels of HP1-γ (CBX3) [encoded by HP1-γ (CBX3)] are known to accelerate HCC cell proliferation, thus suggesting that HP1-γ (CBX3) is a crucial oncogene in hepatocellular carcinoma." (PMID 34046352, 2021). "Non-coding RNAs play a crucial role in the regulation of CBX3, particularly in the context of hepatocellular carcinoma (HCC)." (PMID 39272883, 2024). "Recent studies have shown that CBX3 overexpression promotes tumorigenesis and progression in numerous malignancies, especially hepatocellular carcinoma, glioblastoma, and colon cancer." (PMID 37674204, 2023). "Results revealed that high expression of CBX1, CBX2, CBX3, CBX6, and CBX8 was associated with poor survival rates of hepatocellular carcinoma patients." (PMID 35677563, 2022). "Among the predicted PΨgs, we identified the ubiquitous CBX3-PΨg, which has been shown to form a chimeric transcript with C15ORF57 and has been associated to glioblastoma and hepatocellular cancer." (PMID 35114952, 2022). "The resulting nomogram revealed that CBX3 and T stages were significantly correlated with prognosis of hepatocellular carcinoma patients." (PMID 35677563, 2022). "CBX3 expression is also dysregulated in osteosarcoma and hepatocellular carcinoma." (PMID 39272883, 2024). "In addition, CBX3 promoted the progression in hepatocellular carcinoma, and predicted poor survival." (PMID 37436074, 2023). "Results of the present study indicated that CBX3 expression was strongly correlated with infiltration of DC cells, suggesting that CBX3 may be a key target for future development of DC cells in hepatocellular carcinoma." (PMID 35677563, 2022). "Collectively, these findings suggest that CBX3 could be a biomarker for predicting prognosis of hepatocellular carcinoma patients." (PMID 35677563, 2022). "Overall, these findings indicate that CBX3 is a novel biomarker for hepatocellular carcinoma, and a potential target for future development of therapies for HCC treatment." (PMID 35677563, 2022). "However, the prognostic value and functions of CBX3/HP1γ in hepatocellular carcinoma (HCC) remain unclear." (PMID 31375643, 2019). "Patient baseline and correlation between CBX3/HP1γ expression and clinicopathologic characteristics in hepatocellular carcinoma (HCC)." (PMID 31375643, 2019). "Higher expression of CBX7 was correlated with better prognosis in hepatocellular carcinoma, whereas CBX1, CBX2, CBX3, CBX6 and CBX8 were identified as independent prognostic factors for poor overall survival." (PMID 35637952, 2022).
prostate carcinoma (14 papers, 2017 to 2025). A carcinoma that arises from epithelial cells of the prostate gland. "The findings show that CBX3 is transcriptionally upregulated by BRD4 in castration‐resistant prostate cancer (CRPC) cells." (PMID 37949681, 2023). "In prostate cancer, CBX3 has been demonstrated to regulate androgen receptor signaling and upregulate c-Myc to promote tumor progression." (PMID 34785774, 2022). "Elevated protein expression of CBX3 was involved in unfavorable prognosis in prostate cancer, and it also was an independent prognostic marker." (PMID 35155439, 2022). "In prostate cancer, CBX3 protein expression was increased, and Cox survival analysis showed that it was an independent prognostic marker." (PMID 32742466, 2020). "Itsumi and Chang etal. proposed that a CBX3/miR-451a/c-Myc regulatory circuitry exists in prostate cancer and that it plays a crucial role in tumor progression." (PMID 31375643, 2019). "Although CBX3/HP1γ protein staining was weak in some lymphomas, prostate cancer and renal cancer, CBX3/HP1γ mRNA expression was higher in 20 types of cancer than in normal tissues (p value: 0.01, fold change: 1.5, gene rank: 10%)." (PMID 31375643, 2019). "Additionally, the correlation between CBX3 protein expression and clinically unfavorable outcomes was stronger than the correlation in prostate cancer." (PMID 32742466, 2020). "In prostate cancer, CBX3 expression was elevated, and might be an independent factor to predict the biochemical recurrence of prostate cancer after radical prostatectomy." (PMID 29903985, 2018). "Then we further clarified the expression of CBX family members in prostate cancer, which result showed that CBX5, CBX6 and CBX7 were significantly down-regulated in prostate cancer tissues, while CBX3, CBX2, CBX4 and CBX8 was notably up-regulated." (PMID 40861818, 2025). "Additionally, the potential for CBX3 to influence prostate cancer growth by modulating the PI3K/AKT pathway has been suggested; however, the significance of the interplay of CBX3 with the PI3K/AKT pathway in ccRCC is unclear." (PMID 37674204, 2023).
lung adenocarcinoma (13 papers, 2013 to 2024). A carcinoma that arises from the lung and is characterized by the presence of malignant glandular epithelial cells. "Evidence suggests that smoking-associated upregulation of CBX3 can accelerate the progression of lung adenocarcinoma (LUAD) by activating the ARHGAP24/Rac1 signaling axis." (PMID 39272883, 2024). "CBX3 overexpression has been linked to the advancement of lung adenocarcinoma via activation of the RAC1 pathway, a component of the Wnt signaling network." (PMID 39272883, 2024). "Together, these data suggest that CBX3 plays a role in modulating smoking-associated lung adenocarcinoma cell growth." (PMID 34785774, 2022). "Among the three HP1 proteins, CBX3 is the histone reader protein that is highly expressed in lung adenocarcinoma (LUAD)." (PMID 39272883, 2024). "Significant upregulation of CBX3 has been found in a variety of cancers, including lung adenocarcinoma (LUAD), non-small cell lung cancer (nSCLC), and tongue squamous cell carcinoma (TSCC)." (PMID 33014884, 2020). "Kaplan–Meier analysis demonstrated that high expressions of CBX1 and CBX3 are correlated with overall survival, disease‐specific survival, disease‐free interval, and progression‐free interval for patients with lung adenocarcinoma (LUAD)." (PMID 32894652, 2020). "Alam etal. demonstrated that CBX3/HP1γ promoted proliferation, colony formation, and migration in lung adenocarcinoma (LUAD) cells by directly repressing NCOR2 and ZBTB7A." (PMID 31375643, 2019). "Moreover, CBX3 facilitates the progression of lung adenocarcinoma by directly repressing NCOR2 and ZBTB7A expression." (PMID 34395271, 2021). "Elevated CBX3 mRNA levels were involved in poor prognosis in lung adenocarcinoma patients." (PMID 32742466, 2020). "We report here that CBX3 (Chromobox 3) may be an independent prognostic biomarker in lung adenocarcinoma (LUAD)." (PMID 32894652, 2020). "These genes include SMARCC1, TRA2B, CBX3 and PRPF6 that show the same upregulation pattern as EGFR in lung adenocarcinoma and we have reported all the mentioned genes for the first time in lung adenocarcinoma." (PMID 23874428, 2013). "We found that CBX3 was downregulated in the nontumor lung tissue compared to the lung adenocarcinoma (P = 0.0031)." (PMID 34785774, 2022). "Similarly, through IHC staining, we detected CBX3 expression in a tissue microarray of lung adenocarcinoma specimens (nontumor lung tissues (n = 8) and lung adenocarcinoma tissues (n = 59), cat." (PMID 34785774, 2022).
colon carcinoma (11 papers, 2017 to 2024). "Overall, our model predicts that CBX3 is required for fine-tuning the expression of IFNγ-stimulated immune genes, which makes CBX3 implicated in modulating colon inflammatory response as well as colon cancer chemo-resistance." (PMID 38684864, 2024). "LncRNA SNHG17 elevates proliferation, migration, and invasion via serving as miR-375 sponge to control the expression of chromobox 3 (CBX3) in colon cancer." (PMID 33246471, 2020). "CBX3 promotes cell proliferation in colon cancer and tongue squamous cell carcinoma by suppressing the p21 activity." (PMID 32682359, 2020). "CBX3 can promote the formation of colon cancer by inhibiting the expression of CDK6/p21, which are cell cycle (G1 phase to S phase) related genes." (PMID 31138312, 2019). "In this study, we show that CBX3 protein levels are significantly increased in primary colon cancer tissues." (PMID 28193906, 2017). "To investigate the effect of the deletion of CBX3 on colon cancer cell growth, we used flow cytometry to analyze cell cycle and apoptosis." (PMID 28193906, 2017). "To investigate the mechanism by which CBX3 promotes colon cancer, we deleted CBX3 in HCT116 with the CRISPR/Cas9 editing system and found that cell cycle progression was curbed in G1 phase and proliferation was inhibited." (PMID 28193906, 2017). "Cell proliferation was also analyzed by MTS assay, and the deletion of CBX3 in colon cancer cells evidently reduced cell growth rate." (PMID 28193906, 2017). "We found high abundances of CDK6 accompanied by reduced or undetectable expression of p21, where CBX3 expression was significantly upregulated in colon cancer tissue." (PMID 28193906, 2017). "In conclusion, these findings provide a new perspective for understanding CBX3 as an oncogenic molecule in colon cancer." (PMID 28193906, 2017). "The deletion of CBX3 in colon cancer cells curb cell cycle progression (G1 phase to S phase) suppress cell proliferation in vitro and tumor growth in vivo, where CDK6 and p21 are consistently upregulated." (PMID 28193906, 2017). "A specified number of cells were seeded into plates and the deletion of CBX3 in the colon cancer cell line significantly reduced the numbers of colonies per dish after incubation for 5 days." (PMID 28193906, 2017). "In this study, we show that CBX3 in colon cancer cells promotes the progression of the cell cycle and proliferation in vitro and in vivo." (PMID 28193906, 2017). "To investigate the mechanism by which CBX3 directly promotes colon cancer cell proliferation in vivo, we performed xenograft tumor growth assays in nude mice and the size and weight of tumors were measured after 24 days." (PMID 28193906, 2017). "Therefore, we identify a new mechanism by which CBX3 promotes colon cancer progression via the CDK6/p21 pathway during cell cycle." (PMID 28193906, 2017). "We had identified that the deletion of CBX3 increases CDK6 and p21 expression in colon cancer cells." (PMID 28193906, 2017). "Taken together, our data indicates that CDK6 knocked down promotes colon cancer cell proliferation in the absence of CBX3." (PMID 28193906, 2017). "We had previously found that CBX3 can inhibit the expression of CDK6 and P21 in colon cancer." (PMID 28193906, 2017). "We find that p21 is nearly absent from colon cancer tissues, but CBX3 significantly increases." (PMID 28193906, 2017). "To further confirm that CBX3 promotes colon cancer progression via regulating the expression of CDK6/p21, we examined the expression of CBX3, CDK6 and p21 in human non-cancerous tissue (NCA) and cancerous tissue (CA)." (PMID 28193906, 2017).
non-small cell lung carcinoma (11 papers, 2017 to 2024). A group of at least three distinct histological types of lung cancer, including non-small cell squamous cell carcinoma, adenocarcinoma, and large cell carcinoma. "In patients with non-small cell lung cancer (NSCLC), elevated CBX3 expression is associated with poor survival." (PMID 35464847, 2022). "And in non-small-cell lung cancer tumor-initiating cells, CBX3 and H3K9me3 are significantly increased and inhibited DNA damage related to antineoplastic therapy efficacy." (PMID 33273987, 2020).